PFN3 (profilin 3)
Description:
Binds to actin and affects the structure of the cytoskeleton. Slightly reduces actin polymerization. Binds to poly-L-proline, phosphatidylinositol 3-phosphate (PtdIns(3)P), phosphatidylinositol 4,5-bisphosphate (PtdIns(4,5)P2) and phosphatidylinositol 4-phosphate (PtdIns(4)P). May be involved in spermatogenesis.
Synonyms: profilin-3
Tractability: PROTAC: its protein half-life has been measured.
Gene: Protein-coding gene on chromosome 5 (177,400,109 to 177,400,661, reverse strand). Ensembl gene ENSG00000196570.
Subcellular location: Cytoplasm, cytoskeleton; Nucleus
Subcellular location (Human Protein Atlas): Cytosol; Vesicles
Gene Ontology:
Molecular function: actin binding
Biological process: positive regulation of actin filament bundle assembly; regulation of actin filament polymerization; actin cytoskeleton organization
Cellular component: cytoplasm; cytoskeleton; nucleus
Genetic constraint (gnomAD): Loss-of-function variants: 7 observed, 5.63 expected, observed/expected ratio (o/e) 1.24, 90% interval 0.69 to 1.88. That is too few expected variants to judge how well the gene tolerates losing a copy. Missense variants: 251 observed, 201.41 expected, observed/expected ratio (o/e) 1.25, 90% interval 1.12 to 1.38. Synonymous variants: 112 observed, 90.07 expected, observed/expected ratio (o/e) 1.24, 90% interval 1.07 to 1.46.
Homologues: Orthologues: chimpanzee PFN3 (100% identical), macaque PFN3 (98% identical), pig PFN3 (90% identical), rat Pfn3 (89% identical), mouse Pfn3 (88% identical), guinea pig PFN3 (82% identical). Paralogues in human: PFN1 (44% identical), PFN2 (42% identical).
Diseases named in the same sentence as PFN3 in open-access papers:
PFN3 is named in the same sentence as 4 diseases in open-access papers, as found by Europe PMC text mining. Sharing a sentence is not in itself a finding about the gene and the disease. The quoted sentences say what the papers report.
Globozoospermia (1 paper, 2021). Any structural anomaly of the acrosome resulting in a round sperm head. "In this study, we have shown that deletion of Pfn3 results in male subfertility hallmarked by reduced sperm count/vitality with sperm displaying type II globozoospermia." (PMID 34869336, 2021). "Pfn3–/– males are subfertile, displaying a type II globozoospermia." (PMID 34869336, 2021).
male infertility (1 paper, 2021). The inability of the male to effect fertilization of an ovum after a specified period of unprotected intercourse. "In conclusion, our study highlights the requirement of Pfn3 during spermiogenesis specifically in acrosome biogenesis and adds this gene to the growing catalog of genes potentially involved in human male infertility." (PMID 34869336, 2021).
nephrolithiasis (1 paper, 2020). The presence of a calculus in the pelvis of the kidney; this is most often composed of mineral salts and proteins. "Genetic variation of PFN3 is significantly related to nephrolithiasis of Japanese individuals." (PMID 33381555, 2020).
PFN3 also shares sentences with these, for which no sentence is quoted: cancer (1 paper).